DUOX2 (dual oxidase 2)
Diseases named in the same sentence as DUOX2 in open-access papers (continued):
Sharing a sentence is not in itself a finding about the gene and the disease.
inflammatory bowel disease (19 papers, 2013 to 2025). A spectrum of small and large bowel inflammatory diseases of unknown etiology. "This carries implications for inflammatory bowel disease patients with DUOX2 loss-of-function variants as the intestinal barrier will be vulnerable to transfer of microbes and microbial products, resulting in chronic inflammation." (PMID 40715145, 2025). "DUOX2 is associated with chronic inflammation including chronic inflammatory preneoplastic disorders, inflammatory bowel disease, and chronic pancreatitis." (PMID 33748270, 2021). "Duox2 has also been implicated in the pathogenesis of chronic inflammatory, pre-neoplastic conditions, such as inflammatory bowel disease and chronic pancreatitis." (PMID 23404210, 2013). "Moreover, DUOX2 is closely linked to inflammatory responses, as its upregulation in conditions such as inflammatory bowel disease enhances ROS-mediated immune activation and cytokine release." (PMID 41383848, 2025). "The expression of Duox2 in the gastrointestinal tract has recently been demonstrated to be under the control of pro-inflammatory cytokines that are known to be associated with inflammatory bowel disease." (PMID 23404210, 2013). "As other studies have revealed the role of DUOX2 as a risk factor for Inflammatory Bowel Disease (IBD) and its implications for CRC progression, this lncRNA may contribute to CRC progression through regulating pathways involving immune response and chronic inflammation." (PMID 40666182, 2025). "For example, inflammatory diseases such as inflammatory bowel disease (IBD) are associated with certain antimicrobial genes like DUOX2 and DUOXA2, and elevated DUOX2 levels in the intestine often indicate increased inflammation and mucosal dysbiosis." (PMID 38101300, 2024). "In 2015, a gene defect in DUOX2 was reported in patients with early-onset inflammatory bowel disease." (PMID 40153427, 2025). "It has been reported that strong DUOX2 expression accelerates the development of colorectal and pancreatic cancers in patients with inflammatory bowel disease and chronic pancreatitis, respectively." (PMID 31706280, 2019). "By its function and regulation, DUOX2 is a candidate gene for inflammatory bowel diseases (IBD), chronic inflammatory disorders of the gastrointestinal tract." (PMID 29977049, 2018). "DUOX2 is upregulated in inflammatory bowel disease and colorectal cancers and, alongside DUOXA2, is a primary driver of H2O2 production in mucosal tissues, which may contribute to chronic inflammation and reactive oxygen species (ROS)-related DNA damage." (PMID 34700376, 2021). "Literature data showed that NOX1 and DUOX2 have significant roles in Helicobacter pylori-induced gastric inflammation, inflammatory bowel disease (IBD), and tumors." (PMID 33573222, 2021). "and p.P303R) of DUOX2 are thought to be crucial in some patients with inflammatory bowel disease (IBD), especially those with very early onset IBD33–35." (PMID 33628596, 2021). "In colon epithelial cells 5-HT increases ROS levels by activating NOX2 and DUOX2 linking the changes in 5-HT content in the gut of patients with inflammatory bowel disease (IBD) to its pathogenesis." (PMID 33807720, 2021). "By analyzing publicly available expression data of various clinical studies derived from ileum and colon tissue samples of inflammatory bowel disease (IBD) patients, we found that DUOX2 expression was upregulated in the mucosa of IBD patients compared to healthy controls (HC)." (PMID 37891968, 2023).
colitis (17 papers, 2012 to 2026). Inflammation of the colon. "Apocynin mitigated stress-induced ROS/RNS production and body weight loss even prior to colitis onset, reduced colonic expression of key oxidative enzymes, especially DUOX2, and alleviated both chemically and infectious colitis severity." (PMID 41418891, 2025). "Functional assays such as knockdown or overexpression of PLCΒ3 and DUOX2 in colonic epithelial cells or murine models of colitis would be critical next steps to determine causality." (PMID 40892863, 2025). "DUOX2 is a critical modulator in mutualistic host-microbiota interactions, which has been reported to be involved in colitis-associated colorectal tumorigenesis." (PMID 38659246, 2024). "In line with this, human genetic studies have found that loss-of-function mutations in ROS-producing enzymes predispose to IBD: patients (especially with very-early-onset IBD) carrying defective NOX2 (as in chronic granulomatous disease) or mutations in NOX1/DUOX2 often develop colitis." (PMID 40860650, 2025). "DUOX2 in intestinal epithelial cells regulates host–microbiome interactions and homeostasis; its deletion alters the microbiome and reduces colitis susceptibility by limiting ROS-mediated damage, suggesting DUOX2 as a therapeutic target for intestinal inflammation." (PMID 40428318, 2025). "Pharmacological inhibition of DUOX2 with Compound 521 reduced oxidative stress, ameliorated colitis, and partially restored microbial balance." (PMID 41897439, 2026). "Stress exacerbated disease severity in both infectious (C. rodentium) and chemically induced (DSS) colitis, amplifying colonic expression of Duox2, Nos2, and Ccl2, especially." (PMID 41418891, 2025). "UMSCs suppressed DUOX2‐mediated oxidative stress to attenuate DSS‐induced colitis by regulating T cell‐mediated immunity." (PMID 40842289, 2025). "In the murine experiment, UMSCs suppressed DUOX2‐mediated oxidative stress to attenuate DSS‐induced colitis by regulating T cell‐mediated immunity." (PMID 40842289, 2025). "Duox2 WT and CKO mice were administered with AOM and DSS to establish a colitis-associated tumorigenesis." (PMID 38659246, 2024). "In summary, our data demonstrates that deletion of epithelial DUOX2 protects from acute DSS-induced colitis potentially via an improved regenerative response and mucosal healing." (PMID 37891968, 2023). "For example, in animal models, could enhancing epithelial NADPH oxidase activity (e.g., by administering low levels of ROS donors or gene therapy to boost NOX1/DUOX2 function) reduce colitis severity?" (PMID 40860650, 2025). "In addition, western blotting and immunofluorescence showed that elevated DUOX2 expression in the colonic epithelium of DSS‐induced colitis models was down‐regulated by UMSCs, suggesting that UMSC therapy inhibited DUOX2‐mediated oxidative stress." (PMID 40842289, 2025). "Therefore, we have selected Duox2 and Pla2g4f as prime candidates for further analysis of their roles in murine colitis models and human IBD." (PMID 22970191, 2012). "Furthermore, Duox2∆IEC mice with a specific deletion of DUOX2 in the intestinal mucosa were protected from acute experimental colitis, unlike Duoxa−/− mice with systemic inactivation of DUOX1 and DUOX2, which did not display an altered susceptibility to experimental colitis." (PMID 37891968, 2023). "Among the remaining 10 genes, we identified Pla2g4f and Duox2 as the most likely colitis gene candidates, because GPX metabolizes PLA2G4F and DUOX2 products." (PMID 22970191, 2012). "Intestinal epithelial cell-specific Duox2 knockout (KO) mice exhibited reduced mucosal ROS, preserved barrier integrity, and attenuated dextran sodium sulfate (DSS)- and 2,4,6-trinitrobenzene sulfonic acid (TNBS)-induced colitis." (PMID 41897439, 2026). "DUOX2 expression was also increased; however, this increase was moderate as compared to that of NOX1, suggesting a predominant role of NOX1 in TNFα-induced colitis." (PMID 25276054, 2014).
colitis (continued). "We then explain the rationale for why we chose Pla2g4f and Duox2 as the top colitis gene candidates rather than eight other genes that included Bub1b, Plcb2, Casc5, Chac1, Oip5, Pla2g4e, Trp53bp1 and Slc28a2." (PMID 22970191, 2012).
thyroid dyshormonogenesis (16 papers, 2014 to 2025). "In total, 92 of 132 (69.70%) mutations were related to thyroid dyshormonogenesis [DUOX2 (n = 49), TG (n = 35), and TPO (n = 8)]." (PMID 30420871, 2018). "To determine the inheritance mode of CH caused by thyroid dyshormonogenesis, we analyzed 22 family trios, in which the probands carried compound heterozygous mutations in genes involved in thyroid hormone synthesis (DUOX2, DUOXA2, TPO and TG)." (PMID 29650690, 2018). "All forms of thyroid dyshormonogenesis were considered to be inherited in an autosomal recessive manner, with the exception of thyroid dyshormonogenesis caused by DUOX2 mutations, which was thought to be transmitted in an autosomal dominant manner." (PMID 29650690, 2018). "The c.1588A > T mutation in DUOX2, which is responsible for thyroid dyshormonogenesis, was highly recurrent, with a prevalence of 1/40,000." (PMID 30420871, 2018). "In addition, 10%–15% of cases are caused by thyroid dyshormonogenesis, which is associated with mutations in thyroid DUOX2, DUOXA2, TG, and TPO." (PMID 37252044, 2023). "The DUOX2 gene is associated with thyroid dyshormonogenesis 6 phenotype (OMIM#607200)." (PMID 33815474, 2021). "DUOX2 mutations are the most powerful genetic predisposing factors for thyroid dyshormonogenesis." (PMID 31595719, 2019). "According to previous studies, mutations in DUOX2 are responsible for thyroid dyshormonogenesis." (PMID 30420871, 2018). "Because H2O2 is the limiting factor for thyroglobulin iodination when the iodide supply is normal, DUOX2 mutations often cause thyroid dyshormonogenesis and are linked to CH associated with goiter or a thyroid gland of normal size in the presence of an iodide organification defect." (PMID 29650690, 2018). "The third variant, c.3449 A>G, p.Tyr1150Cys in the DUOX2 gene, is correlated in the OMIM database with thyroid dyshormonogenesis 6 (OMIM# 607200)." (PMID 41300763, 2025). "Among the 29,601 newborns, 62 tested positive for the DUOX2 gene, which is related to thyroid dyshormonogenesis." (PMID 39728398, 2024). "In the 3,158 newborns include by the research, 10 were tested positively from DUOX2 gene which related to thyroid dyshormonogenesis." (PMID 37252044, 2023). "Genetic analysis of DUOX2 hotspots (including 11 exons) by PCR-direct sequencing was performed in 52 patients with suspected thyroid dyshormonogenesis (SDH) according to thyroid ultrasound at diagnosis." (PMID 33072985, 2019). "Mutations in genes critical for TH biosynthesis, including sodium iodide symporter (NIS; SLC5A5), pendrin (PDS; SLC26A4), thyroglobulin (TG), thyroperoxidase (TPO), thyroid stimulating hormone receptor (TSHR), and dual oxidase 2 (DUOX2), have been causally linked to thyroid dyshormonogenesis." (PMID 38281222, 2024).
pancreatic cancer (15 papers, 2013 to 2025). "However, the regulatory mechanisms governing the DUOX2/ROS axis in pancreatic cancer and its causal relationship with malignant transformation remain poorly characterized." (PMID 41154358, 2025). "Collectively, these findings indicate that TCN1 promotes pancreatic cancer malignancy by activating DUOX2-dependent signaling, which drives ROS generation and facilitates aggressive tumor behavior." (PMID 41154358, 2025). "In a previous study, we established the functional roles of TCN1 and DUOX2 in pancreatic cancer progression and their regulatory relationships." (PMID 41154358, 2025). "EdU proliferation and colony formation assays showed that DUOX2 knockdown suppressed pancreatic cancer cell proliferation, whereas DUOX2 overexpression enhanced these malignant phenotypes." (PMID 41154358, 2025). "To further delineate the mechanism through which the TCN1/STAT4/DUOX2 axis promotes pancreatic cancer malignancy, we systematically performed functional rescue experiments in BxPC-3 and PANC-1 cells." (PMID 41154358, 2025). "The study emphasizes the significance of DUOX2 in pancreatic cancer, establishing a connection between its expression, microbial defense, and IL‐17A levels." (PMID 38585232, 2024). "Subsequent functional experiments provided confirmation of IL‐17A‐mediated regulation of DUOX2 in pancreatic cancer cells." (PMID 38585232, 2024). "Increased expression of DUOX2 has been reported in human pancreatic cancer cells when being exposed to IFN-γ." (PMID 35607956, 2022). "At the same time, the authors demonstrated the upregulation of DUOX2 expression in vivo in pancreatic cancer xenografts and in patients with chronic pancreatitis." (PMID 28626501, 2017). "In a prior investigation, we demonstrated that BxPC-3 pancreatic cancer cells passaged for one cycle as xenografts in immunocompromised mice significantly up-regulated the expression of DUOX2." (PMID 27637085, 2016). "In this study, we found that increased DUOX2 expression was associated with a significant increase in the expression of the pro-angiogenic proteins, HIF-1α and VEGF-A, in human pancreatic cancer cells." (PMID 27637085, 2016). "We previously reported that several human pancreatic cancer cell lines up-regulate the expression of DUOX2 and DUOXA2 in response to treatment with the pro-inflammatory cytokines IFN-γ and LPS, although to varying degrees." (PMID 27637085, 2016). "To understand the potential relevance of our studies conducted with PDAC cell lines to the clinical behavior of pancreatic cancer, we evaluated the expression of DUOX2 in vivo." (PMID 27637085, 2016). "DUOX2 expression levels were increased in 9/13 pancreatic cancers when these samples were matched against adjacent pancreatic tissues that were without evidence of malignancy." (PMID 27637085, 2016). "Previously, we demonstrated that IFN-γ upregulates the mRNA expression of Duox2 in BxPC-3 human pancreatic cancer cells in a time- and concentration-dependent manner." (PMID 23404210, 2013). "Duox2 expression detected by Duox S-12 was functionally coupled to the generation of H2O2 in pancreatic cancer cells that expressed Duox2 and its cognate maturation factor DuoxA2." (PMID 23404210, 2013). "Using the Duox S-12 monoclonal antibody, we confirmed our previous results demonstrating that IFN-γ upregulates Duox2 at the protein as well as mRNA levels in BxPC-3 human pancreatic cancer cells." (PMID 23404210, 2013). "Analysis of the TCGA and GTEx datasets revealed that DUOX2 expression was significantly higher in pancreatic cancer tissues than in normal tissues, and its elevated expression correlated with shorter overall patient survival, showing that DUOX2 is a potential oncogenic driver." (PMID 41154358, 2025). "In addition, multivariate analysis suggested that high DUOX2 expression, head of pancreatic cancer, and advanced TNM stages were independent prognostic factors of poor OS." (PMID 33748270, 2021).
pancreatic cancer (continued). "DUOX2 expression, unlike that of the DUOX1 homolog, is associated with progression of pancreatic cancer; the pro-inflammatory cytokine IFN-γ triggers Stat1-mediated DUOX2/DUOXA2 up-regulation in pancreatic cancer cell lines, contributing to increased intra- and extracellular ROS production." (PMID 28578276, 2017). "Furthermore, expression of the DUOX2 gene and protein is increased in various human pancreatic cancer cell lines following IFN-γ and/or lipopolysaccharide [LPS] stimulation." (PMID 27637085, 2016). "Transwell migration/invasion and wound-healing assays further revealed that DUOX2 knockdown attenuated tumor cell migratory and invasive capacities, whereas DUOX2 overexpression robustly promoted these behaviors, confirming the critical role of DUOX2 in pancreatic cancer metastasis." (PMID 41154358, 2025). "However, whether TCN1 drives pancreatic cancer progression through DUOX2-dependent signaling remains unverified." (PMID 41154358, 2025). "However, the prognostic significance and the biological function of DUOX2 expression with pancreatic cancer (PC) still remain unclear." (PMID 33748270, 2021). "Increased DUOX2-derived ROS production is also associated with increased VEGF and HIF-1α expression in pancreatic cancer cell lines; evaluation of malignant versus matched non-malignant pancreatic tissues also demonstrated DUOX2-related up-regulation of VEGF expression." (PMID 28578276, 2017). "Analysis of pancreatic cancer tissues from the GEPIA database revealed a strong positive correlation between TCN1 and DUOX2 expression, further supporting their regulatory relationship." (PMID 41154358, 2025). "In particular, the H2O2-generating Nox isoform dual oxidase 2 [DUOX2] can be highly expressed in patients with chronic pancreatitis, or PDAC, as well as in human pancreatic cancer xenografts in mice." (PMID 27637085, 2016). "IFN-γ significantly induced both DUOX2 and VEGF-A transcription in the BxPC-3 pancreatic cancer cell line (P < 0.001 vs. solvent-treated cells)." (PMID 27637085, 2016). "Taken together, these results demonstrated that DUOX2 expression and VEGF-A expression are up-regulated in concert in IFN-γ-responsive pancreatic cancer cells." (PMID 27637085, 2016). "Significant increases in DUOX2 and VEGF-A mRNA expression were demonstrated in surgically-resected human pancreatic cancer specimens compared to adjacent normal pancreatic tissues." (PMID 27637085, 2016). "We previously demonstrated that the pro-inflammatory cytokines IFN-γ and LPS increased DUOX2 expression, with concomitant H2O2 production and DNA damage, in human pancreatic cancer cell lines by activating signal transduction through both Stat1 and NF-κB." (PMID 27637085, 2016). "In the same study, we found that Duox2 expression in MIA PaCa-2 and PANC-1 human pancreatic cancer cell lines was unresponsive to IFN-γ exposure." (PMID 23404210, 2013). "In addition to protein levels, NSD3 induces global H3K36 dimethylation in pancreatic cancer cells and influences the mRNA levels for genes including ADAM28, ADAM9, BIRC3, CXCL5, DUOX2, GABRP, ITGB6, and RAB11FIP1." (PMID 37062069, 2023). "As a potent oncogene, the expression of DUOX2 has been shown to be significantly upregulated in several cancer types including lung, cervical, colon, rectal, stomach, and pancreatic cancers when compared with adjacent nonmalignant tissues." (PMID 33748270, 2021). "Furthermore, concomitant treatment of a pancreatic cancer cellline with INF-γ and LPS increased DUOX2 expression and activity throughTLR4-NF-κB activation, which decreased cell proliferation, and increasedapoptosis and DNA damage." (PMID 32453337, 2020). "Finally, the expression of both DUOX2 and VEGF-A was rapidly increased when human pancreatic cancer cells were propagated as xenografts in immunocompromised mice." (PMID 27637085, 2016).
pancreatic cancer (continued). "Among its specific interaction partners, DUOX2 requires the maturation factor DUOXA2 for the formation of a functional, H2O2-producing complex; the expression of DUOXA2, like DUOX2, is also up-regulated by IFN-γ exposure in human pancreatic cancer cells." (PMID 27637085, 2016). "To evaluate whether VEGF-A expression is increased in other human pancreatic cancer cell lines following stimulation with IFN-γ and subsequent up-regulation of DUOX2, we compared BxPC-3 cells with the AsPC-1 and CFPAC-1 lines." (PMID 27637085, 2016).